PCDHGB5 (protocadherin gamma subfamily B, 5)
Description:
Potential calcium-dependent cell-adhesion protein. May be involved in the establishment and maintenance of specific neuronal connections in the brain.
Synonyms: PCDH-gamma-B5
Tractability: Antibody: UniProt places it where antibodies can reach, with medium confidence; UniProt predicts a signal peptide or a membrane-spanning region; its Gene Ontology location is reachable by antibodies, with medium confidence.
Gene: Protein-coding gene on chromosome 5 (141,397,947 to 141,512,975, forward strand). Ensembl gene ENSG00000276547.
Subcellular location: Cell membrane
Subcellular location (Human Protein Atlas): Plasma membrane; Vesicles; Cytosol; Nucleoplasm
Gene Ontology:
Molecular function: cell adhesion molecule binding; calcium ion binding
Biological process: cell adhesion; homophilic cell-cell adhesion
Cellular component: extracellular exosome; plasma membrane; membrane
Genetic constraint (gnomAD): Loss-of-function variants: 48 observed, 60.16 expected, observed/expected ratio (o/e) 0.8, 90% interval 0.63 to 1.01. The upper end of that interval is the gene's LOEUF score, 1.01, which puts it in group 4 of 6, group 1 being the genes least tolerant of losing a copy. Missense variants: 1,038 observed, 1,100.3 expected, observed/expected ratio (o/e) 0.94, 90% interval 0.9 to 0.99. Synonymous variants: 444 observed, 470.19 expected, observed/expected ratio (o/e) 0.94, 90% interval 0.87 to 1.02.
Homologues: Orthologues: macaque PCDHGB5 (98% identical), rat Pcdhgb7 (85% identical), mouse Pcdhgb5 (85% identical), dog PCDHGB5 (76% identical), rabbit PCDHGB5 (74% identical), tropical clawed frog pcdhgb5 (39% identical). Paralogues in human: PCDHGB4 (85% identical), PCDHGB6 (74% identical), PCDHGB1 (74% identical), PCDHGB2 (73% identical), PCDHGB7 (72% identical), PCDHGB3 (71% identical), PCDHGA5 (54% identical), PCDHGA6 (53% identical), PCDHGA11 (53% identical), PCDHGA12 (53% identical), PCDHGA1 (53% identical), PCDHGA9 (52% identical), and 49 more.
Diseases named in the same sentence as PCDHGB5 in open-access papers:
PCDHGB5 is named in the same sentence as 1 disease in open-access papers, as found by Europe PMC text mining. Sharing a sentence is not in itself a finding about the gene and the disease. The quoted sentences say what the papers report.
infection (1 paper, 2018). The state of being infected such as from the introduction of a foreign agent such as serum, vaccine, antigenic substance or organism. "We now show that a subset of these proteins are degraded early during infection, including PCDHGB5, supporting the suggestion that these might be NK or T cell ligands or cellular receptors for HCMV." (PMID 30122656, 2018).